BAX (BCL2 associated X, apoptosis regulator)
Diseases named in the same sentence as BAX in open-access papers (continued):
Sharing a sentence is not in itself a finding about the gene and the disease.
colorectal cancer (63 papers, 2002 to 2025). A primary or metastatic malignant neoplasm that affects the colon or rectum. "Studies on prognostic significance of TGFBR2 or BAX mononucleotide mutation in MSI-high colorectal cancer." (PMID 21949851, 2011). "We conducted this study to examine the prognostic significance of mononucleotide tract mutations in the coding regions of TGFBR2 or BAX in MSI-high colorectal cancers." (PMID 21949851, 2011). "MSI status, TGFBR2 and BAX mononucleotide tract mutation and survival of colorectal cancer patients." (PMID 21949851, 2011). "MSI status and TGFBR2 or BAX mononucleotide tract mutation in colorectal cancer." (PMID 21949851, 2011). "However, a role of TGFBR2 or BAX mononucleotide mutation in colorectal cancer as a prognostic biomarker remains uncertain." (PMID 21949851, 2011). "BAX gene mutations that reduce transcription levels, or produce dysfunctional protein, have been correlated with increased resistance of cells in lymphocytic leukemia and colorectal carcinoma, respectively." (PMID 20942963, 2010). "Moreover, in some colorectal cancer tissues, as in the LoVo cell line, studies have reported an inactivating frameshift mutation in the BAX gene that make cells relatively resistant to apoptosis and can be at the base of chemoresistance in familial colorectal cancers." (PMID 35457229, 2022). "We conducted this study to test the hypothesis that TGFBR2 or BAX mononucleotide mutations in colorectal cancer were associated with altered tumor behavior (beyond MSI), utilizing a database of 1072 stage I to IV colorectal cancers in two prospective cohort studies." (PMID 21949851, 2011). "In compliance with our findings, a previous study revealed that the methanolic extract of A. absinthium increased the expression levels of BAX and caspases, where it decreased those of Bcl-2 genes in human colorectal cancer HCT-116 cells." (PMID 39770489, 2024). "Knockdown of RPS15 expression reduced the proliferative capacity of colorectal cancer cells and increased BAX‐induced apoptotic cell death." (PMID 38838053, 2024). "In conclusion, our data indicates that UGT8 mediated synthesis of sulfatides controls mitochondrial homeostasis and BAX localization, dictating apoptosis sensitivity of colorectal cancer cells." (PMID 39580596, 2024). "Work #100 reveals that andrographolide can reverse 5-fluorouracil resistance in human colorectal cancer cells by upregulating BAX expression." (PMID 37760489, 2023). "It was reported that chemotherapy-induced pyroptosis is mediated by the BAK/BAX-caspase-3-GSDME pathway in colorectal cancer cells." (PMID 37202386, 2023). "In SW48, another colorectal cancer cell, apoptosis was induced by an increase in BAX and caspase-3, -8, and -9 and the inhibition of PI3K/AKT/STAT-3." (PMID 36142874, 2022). "In HT-29 colorectal cancer cells, Bcl-2 expression was reduced, BAX expression increased, and apoptosis was induced through the PI3K/AKT pathway." (PMID 36142874, 2022). "TRAF3 also plays pro-apoptotic roles in human bladder and colorectal carcinoma cells upon CD40 ligation via BAX/BAK-caspase 9- and ROS- dependent mechanisms." (PMID 34745083, 2021). "Of note, the involvement of both BAX and BAK we observed contrasts with that observed in HCT116 colorectal cancer cells where the S63845/A1331852 combination results in BAX-dependent, but BAK-independent apoptosis." (PMID 31019203, 2019).
colorectal cancer (continued). "BAX alsorender colorectal cancer resistant TRAIL/Apo2L-mediated radiosensitization.Inactivation of BAX and BAK promote epithelial solidtumor growth and resistance to chemotherapy." (PMID 31285648, 2019). "The first aim was to obtain evidence for the actual expression of Bcl2, Bad, BAX, caspase-8, and caspase-9 in pancreatic and colorectal carcinoma cells." (PMID 30686270, 2019). "Due to the inhibitory effect of MCL1 on BAK, the apoptosis of HCT116 colorectal cancer cells in response to either ABT-73729 or the BCL-XL inhibitor A1331852 relies on BAX." (PMID 30478310, 2018). "The high expression of the BAX gene seems to be a negative regulator of autophagy in colorectal cancer cells." (PMID 28035578, 2017). "It has been additionally reported that the BAX protein expression in neoplasm of the digestive system, including liver and colorectal cancers, is downregulated and conversely, Bcl-2 protein is upregulated." (PMID 25202426, 2014). "In colorectal cancer cells, positive associations have been identified between CX26 and the pro-apoptotic gene BCL2-associated X protein (BAX) and between CX26 and the anti-apoptotic gene BCL2-like 1 (BCL2L1)." (PMID 24387126, 2014). "We compared colorectal cancer specific and overall survival between TGFBR2-mutated MSI-high cases and TGFBR2-wildtype MSI-high cases (or between BAX-mutated MSI-high cases and BAX-wild type MSI-high cases)." (PMID 21949851, 2011). "When we separately examined BAX-mutated MSI-high cases and BAX-wildtype MSI-high cases, both groups showed significantly longer colorectal cancer-specific survival compared to MSS/MSI-low cases." (PMID 21949851, 2011). "In this report, we extend these observations to HCT116 colorectal carcinoma cells, which, like neurons, are completely dependent on BAX for apoptosis." (PMID 20942963, 2010). "In line with a previous study on colorectal cancer, we detected a reciprocal correlation between BAX expression and grading." (PMID 17426704, 2007). "A positive immunostaining for cytoplasmic BAX protein is an indicator of its preserved pro-apoptotic function and high BAX protein expression was found to possess positive prognostic value in colorectal cancer." (PMID 11875737, 2002). "Similarly, in HT-29 colorectal cancer cells, activation of the intrinsic apoptosis pathway was demonstrated via upregulation of BAX and downregulation of BCL2." (PMID 35563174, 2022). "In colorectal cancer, mutations have been found in a number of genes with key cellular roles, such as growth factor receptors (TGFBR2 and IGF2R), genes involved in apoptosis (BAX), as well as genes relevant for DNA repair (MSH3, MSH6)." (PMID 20979647, 2010). "The prognostic information of BAX protein expression has been tested for a variety of malignancies, and a recent study reported a significant worse prognosis of those patients with colorectal cancer whose liver metastasis showed low proapoptotic BAX expression." (PMID 17426704, 2007). "A study in 2021 demonstrated that BAX may be a novel target for chemotherapy in colorectal cancer." (PMID 36105400, 2022). "Also AIM2 (absent in melanoma 2), and the pro-apoptotic BAX (BCL2-associated X protein) are inactivated by coding microsatellite mutations in the majority of MSI-H colorectal cancer." (PMID 25816162, 2015).
colorectal cancer (continued). "In colorectal cancer cells treated with CEE, there was a substantial elevation in the mRNA levels of either BAX or caspase-3, with a fold increase of 6.03 and 6.59, respectively, compared to the untreated group." (PMID 39458988, 2024). "For instance, the methanolic extract of Artemisia absinthium induced apoptosis in colorectal cancer through MMP destruction and elevation in BAX/Bcl-2 ratio and caspase-3 expression." (PMID 38966207, 2024). "Densitometric analysis also suggested that BAX and BCL-2 were quantitatively changed in the Δ9-THC treated colorectal cancer cells." (PMID 37837516, 2023). "A further in vitro study conducted on a human colorectal cancer cell line LS180 demonstrated that HT is able to induce apoptosis, enhancing CASP3 gene expression and the BAX:BCL2 ratio." (PMID 38255664, 2023). "One study demonstrated that sorbitol induces apoptosis in colorectal cancer cells by increasing the phosphorylation of p38 MAPK, upregulating the expression of BAX and cleaved caspase-3 while downregulating the expression of Bcl-2." (PMID 37185746, 2023). "Downregulated expression of BAX and BAK in human colorectal cancer lead to chemotherapeutic failure and poor survival rate in patients." (PMID 31551763, 2019). "We have previously established that the colorectal cancer HCT116 p21−/− cell line is a model cell line that requires sustained inhibition of PUMA and BAX by BCL-xL to survive." (PMID 26844698, 2016). "In Affymetrix primeview human GeneChip array, we found six upregulated genes (STAT1, ATF2, TNFRSF10B, TGFBR2, BAX, and SQSTM1) and two downregulated genes (SLC4A7 and CD274) related to apoptosis and proliferation of colorectal cancer cells after hsa_circ_0064559 knockdown." (PMID 37280630, 2023). "In addition, the high expression level of TPM1 enhances the sensitivity of colorectal cancer cells to oxaliplatin via BCL-2 and BAX." (PMID 37854295, 2023). "The current study shows that—in the pancreatic and colorectal cancer cell lines Panc-1, PaTu 8988t, and SW 480—staurosporine does not influence BAX, but influences the anti-apoptotic factor Bcl2." (PMID 30686270, 2019). "Also, salinomycin induces apoptosis in cisplatin-resistant human colorectal cancer cells (Cisp-resistant SW620 cells) by increasing the protein expression of caspases 3, caspase 8, caspase 9 and BAX, but decreasing the protein expression of Bcl-2." (PMID 25531367, 2014). "In conclusion, our large tumor database has shown that, compared to MSS/MSI-low cases, MSI-high colorectal cancer is associated with longer cancer-specific survival, regardless of TGFBR2 or BAX mononucleotide tract mutation status." (PMID 21949851, 2011). "Moreover, BAX levels increased and BCL-2 levels decreased both lung and colorectal cancer cells." (PMID 39838121, 2025). "To evaluate whether sensitivity to AZ’1569 correlated with expression levels of proapoptotic and antiapoptotic BCL-2 family members or DR_MOMP stress dose, we initially determined the basal absolute BCL-2 proteins profiles (BAK, BAX, BCL-2, Bcl-xL, MCL1) in our KRASG12CMT colorectal cancer cells." (PMID 36279564, 2023). "In SW480 and HCT-116 colorectal cancer cells, the downregulation of the β-catenin pathway and increase in the mitochondrial membrane potential depolarization increased the BAX:Bcl-2 ratio and although there was no change in caspase, apoptosis was induced by AIF." (PMID 36142874, 2022).
colorectal cancer (continued). "Therefore, in order to further study the mechanism of RES and VE in promoting colorectal cancer cell apoptosis, western blotting was performed to detect the expression of BCL-2, BAX, caspase-3-, caspase-8-, and caspase-9-related proteins after RES and VE intervention." (PMID 34803703, 2021).
ovarian carcinoma (61 papers, 1999 to 2026). A malignant neoplasm originating from the surface ovarian epithelium. "Earlier studies in our research group found the anticancer properties of DNC are mediated by regulating the expression of lncRNA MEG3 and apoptotic-associated markers of Bcl-2 and BAX in ovarian cancer." (PMID 41480643, 2026). "In ovarian cancer, it was shown that high BAX expression was associated with significant improvement of the percentage of complete remissions after first-line chemotherapy with Paclitaxel and a platinum analogue." (PMID 12592374, 2003). "This study investigated the impact of siRNA-mediated MEG3 silencing in the context of dendrosomal nanocurcumin (DNC) and Oxaliplatin (OXA) treatments on ovarian cancer cell lines, focusing on the expression of genes associated with apoptosis and metastasis, including Bcl-2, BAX, MMP-2, and MMP-9." (PMID 41480643, 2026). "Additionally, treatment of ovarian cancer cells with ABC294640 caused increased expression of BAX, thereby tilting the balance of the bcl-2 family of proteins, which are known to contribute to gemcitabine resistance, in the pro-apoptotic direction." (PMID 27517489, 2016). "One such example of ovarian cancer study demonstrated that ivermectin was found to cause DNA damage through the induction of double-strand DNA breaks and induces intrinsic apoptosis by disrupting the mitochondrial membrane associated with the upregulation of BAX/BCL-2 and cytochrome C release." (PMID 34684095, 2021). "Our previous study has demonstrated that progesterone rapidly induces BAX expression by non‐genomic action mediated by mPRs in ovarian cancer cells." (PMID 40270435, 2025). "Ovarian cancer cell lines were exposed to 100 μM progesterone, and the expression of BAX, a pro‐apoptotic protein, after 1–5 min was examined by western blotting." (PMID 38013666, 2024). "Splice‐switching antisense oligonucleotides targeting BAX exhibit efficient antitumor activity, indicating a promising strategy for therapy of ovarian cancer." (PMID 38342602, 2024). "XTP8 promotes ovarian cancer cell proliferation while inhibiting apoptosis through the BCL2/BAX pathway." (PMID 38717641, 2024). "We demonstrated that the ASOs promoted exon 2 inclusion and generated BAX‐L, which in turn increased the protein level of BAX and induced apoptosis of ovarian cancer cells." (PMID 38342602, 2024). "We also verified that PQBP1 promotes ovarian cancer progression by regulating the aberrant splicing and degradation of BAX." (PMID 38342602, 2024). "Previous studies have reported that PQBP1 regulates AS of BCL‐X in human A549 cells and Ncam‐1 in mouse neurons, and our present work provides strong evidence that PQBP1 regulates AS of apoptotic genes, including BAX, in ovarian cancer cells." (PMID 38342602, 2024). "Here, the authors report that PQBP1 promotes exon skipping and degradation of BAX, which inhibits apoptosis in ovarian cancer cells." (PMID 38342602, 2024). "A tissue-level analysis of the BAX expression in 45 patients with epithelial ovarian cancer showed that patients with higher BAX levels were completely sensitive to chemotherapy, while patients with lower BAX levels were resistant to treatment." (PMID 38003498, 2023). "The aim of this study is to analyze the polymorphisms and expressions of the BCL2, BAX and c-MYC genes in patients with ovarian cancer." (PMID 38003498, 2023).
ovarian carcinoma (continued). "In our study, we analyzed the polymorphisms and expressions of the BCL2, BAX and c-MYC genes in patients with ovarian cancer." (PMID 38003498, 2023). "The experiments conducted in the 3D spheroids model in fact proved that RV synergized with OxPt to induce BAX-mediated cell death in ovarian cancer cells in which BMI-1 was downregulated and LC3 was upregulated." (PMID 34831435, 2021). "In ovarian cancer, campesterol also activated cell death signals, such as cleaved caspase 3, cleaved caspase 9, cytochrome c, BAX, and BAK." (PMID 33802602, 2021). "SRT2183 inhibited the growth of ovarian cancer cells, increased the accumulation of BAX, cleaved-caspase 3 and cleaved-PARP, and decreased the level of anti-apoptotic Bcl-2 and Mcl-1." (PMID 33223507, 2020). "This indicates that the decrease in BCL9 expression inhibited ovarian cancer cell proliferation by promoting the apoptosis of ovarian cancer cells by increasing the BAX/BCL2 expression ratio." (PMID 31827404, 2019). "BCL-2, BCL-XL, MCL-1 and BAX are determinants of apoptosis in response to chemotherapeutic agents, and are variably expressed in ovarian cancers." (PMID 28399108, 2017). "Meanwhile, the increased Bcl-2 and decreased BAX expression levels in miR-17-5p overexpressed ovarian cancer cells confirm that miR-17-5p decreases the paclitaxel-induced apoptosis of ovarian cancer cells." (PMID 26500892, 2015). "The overexpression of miR-17-5p inhibited the ability of chemotherapy to increase BAX expression, while the Bcl-2 expression was increased in miR-17-5p overexpressed ovarian cancer cells." (PMID 26500892, 2015). "Comparable findings have been reported in other contexts; for example, Shi and colleagues demonstrated that curcumin induced an increase in BAX and alterations in Bcl-2 family proteins in ovarian cancer, supporting the notion that phytochemical agents can enhance apoptosis via MEG3-associated axes." (PMID 41480643, 2026). "Taken together, these results indicate that PQBP1‐mediated AS and expression of BAX might play a role in ovarian cancer progression." (PMID 38342602, 2024). "We next sought to develop splice‐switching ASOs targeting BAX for the treatment of ovarian cancer." (PMID 38342602, 2024). "Importantly, we show that PQBP1 regulates the AS and expression of BAX and that PQBP1 depletion leads to exon 2 inclusion that in turn upregulates BAX and triggers apoptosis in ovarian cancer cells." (PMID 38342602, 2024). "Moreover, XTP8 exerts its influence on the apoptosis of ovarian cancer cells through the BCL2/BAX pathway." (PMID 38717641, 2024). "Current knowledge of ovarian cancer provides strong indications that not only establish BOK as an inducer of apoptosis in a BAX- and BAK1-independent manner, but also suggest that BOK can significantly influence the apoptotic response to chemotherapeutic drugs in ovarian carcinoma cells." (PMID 37888203, 2023). "In our study, we also assessed BAX expression levels in ovarian cancer." (PMID 38003498, 2023).